EGFR (epidermal growth factor receptor)
Diseases named in the same sentence as EGFR in open-access papers (continued):
Sharing a sentence is not in itself a finding about the gene and the disease.
lung cancer (continued). "In Matache and Matache (2016) it is specified that mutations of the EGFR are known to be related to lung cancer, interfering with the signaling pathways within the cell triggered to promote cell growth and division (proliferation) and cell survival." (PMID 30233390, 2018). "This is because IFN-γ is the strongest stimulator of PD-L1 expression, and EGF and EGF receptor (EGFR) mutations induce PD-L1 expression with lung cancer progression." (PMID 30126206, 2018). "For example, both p.L858R mutation and exon 19 deletion of epidermal growth factor receptor (EGFR) gene are highly affected when treating lung cancer patients, since the patients who carry these mutations benefit from EGFR tyrosine kinase inhibitors (TKI)." (PMID 29357822, 2018). "We examined 161 patients with primary lung adenocarcinoma to detect EGFR expression in lung cancer cells using immunohistochemistry and determined the correlations of EGFR expression with clinical characteristics, EGFR mutations, and survival time." (PMID 29950164, 2018). "In contrast, the development of T790M mutations in lung cancer cell lines harboring an activating EGFR mutation is well described." (PMID 29448920, 2018). "There is a great need for further investigations to confirm the real contribution of EGFR mutation in lung cancer worldwide." (PMID 30092812, 2018). "It is effective both against common EGFR mutated lung cancers (i.e., deletion in exon 19 or p.Leu858Arg) and exon 20 resistance mutations (p.Thr790Met)." (PMID 29890761, 2018). "Several phase III comparative studies, including NEJ002, have been conducted and have shown that EGFR-TKI is more effective than conventional cytotoxic agents as first-line therapy for EGFR mutation-positive lung cancer." (PMID 29854794, 2018). "In this review, we have summarized some issues considering the role of EGFR in lung cancer, its coding gene, and its promoter gene polymorphisms (SNPs) -216G/T and -191C/A in non-small-cell lung cancer (NSCLC)." (PMID 30406002, 2018). "In cfDNA samples from lung cancer, both platforms were used to detect EGFR sensitizing mutations as well as the EGFR T790M resistance mutation." (PMID 29765524, 2018). "Molecular testing is carried out systematically on all patients with lung cancer in France and EGFR mutations and ALK rearrangements are observed in around 16% of patients." (PMID 30348130, 2018). "Third, lung cancers harboring minor EGFR mutations, which are considered to be refractory to EGFR - TKI, were included in Mt, whereas lung cancers harboring anaplastic lymphoma kinase genes or ROS-1 gene mutations were included in Wt." (PMID 30290774, 2018). "The purpose of this study was to examine the significance of EGFR mutations on the incidence of brain metastases in a population of patients with a stage I to III lung cancer." (PMID 29447182, 2018). "Recently, we demonstrated that isolation of shorter ccfDNA fractions with an offset of 20–50 bp from the mononucleosomal peak of ~167 bp enriched for the EGFR T790M variant in three lung cancer patients." (PMID 30044795, 2018). "For example, it has been shown that ERRFI1/MIG6 expression is associated with EMT and resistance to EGFR inhibitors in lung cancer xenografts." (PMID 30352093, 2018). "In the current investigation, we examined the association between four SNPs in the EGFR gene (rs712829, rs712830, rs2072454, and rs11543848) and lung cancer risk." (PMID 30011810, 2018). "There were 5 studies (409 patients) which investigated associations between 18F-FDG PET and expression of EGFR in lung cancer." (PMID 29983647, 2018). "Osimertinib is efficacious in lung cancer patients with epidermal growth factor receptor (EGFR) mutations and acquired resistance (AR) to EGFR tyrosine kinase inhibitors due to EGFR-T790M mutation (T790M)." (PMID 29930751, 2018).
lung cancer (continued). "Two LC patients with EGFR mutant tumors were eligible for treatment with erlotinib and gefitinib, as established by the International Association for the Study of Lung Cancer." (PMID 29854313, 2018). "In this sense, lung cancer patients harboring EGFR mutations are sensitive to EGFR tyrosine kinase inhibitors (TKIs)." (PMID 29731995, 2018). "Non‐small cell lung cancer (NSCLC) patients carrying EGFR activating mutations treated with gefitinib, a tyrosine kinase inhibitor, will develop drug resistance." (PMID 29901268, 2018). "AXL activation and MED12 loss induced an EMT-like phenotype, which is associated with EGFR-TKI resistance in lung cancer." (PMID 29930762, 2018). "The population in our study was a fairly large cohort to investigate the effectiveness of TKI therapy in patients with compound EGFR-mutated lung cancer." (PMID 30055651, 2018). "Overexpression of EGFR is implicated in the pathogenesis of many human malignancies, including lung cancer." (PMID 29950164, 2018). "We have seen in Epidermal Growth Factor Receptor (EGFR) mutated lung cancer that targeting with a small molecule inhibitor of EGFR can lead to impressive response rates and tumor control better than standard cytotoxic chemotherapy." (PMID 29382159, 2018). "The average frequency of EGFR mutations in Latin America is 30%, as we have describe it on behalf of the Latin American Consortium for the Investigation of Lung Cancer (CLICaP) in two comprehensive studies." (PMID 30093964, 2018). "It has been confirmed that signal transduction between the c-Met and EGFR pathways is closely linked in breast cancer, lung cancer, brain cancer, and other tumors; however, the associated mechanism is still not fully understood." (PMID 29455668, 2018). "Induction of mutant KRAS reduces the numbers of viable lung cancer cells harboring KRAS or EGFR mutations, and the effects can be rescued by inhibiting ERK (A) Reduced numbers of viable LUAD cells after activation of KRAS." (PMID 30475204, 2018). "The best studied mechanisms for acquired resistance (AR) to TKIs in lung cancer are those associated with anti-EGFR and anti-ALK treatments." (PMID 30140389, 2018). "Epidermal growth factor receptor (EGFR) mutations identify patients with lung cancer who derive benefit from kinase inhibitors." (PMID 29212784, 2018). "In this report, we uncovered a novel oncogenic signaling pathway exclusively acting in mutated epidermal growth factor receptor (EGFR) non‐small cell lung cancer (NSCLC) with acquired tyrosine kinase inhibitor (TKI) resistance." (PMID 29449326, 2018). "Clinically, ECOG PS status is considered an important prognostic factor for OS of patients with EGFR mutation-positive lung cancer." (PMID 29805772, 2018). "EGFR mutation is essential for deciding the appropriate chemotherapy, such as erlotinib (Tarceva) or gefitinib (Iressa) for lung cancer." (PMID 30315187, 2018). "Genetic mutation of EGFR has been found in numerous cancers and indicated high correlation with poor prognosis, especially in lung cancers." (PMID 29681982, 2018). "Although TAMs in tumor tissue have been shown to associate with poor response of EGFR-TKIs in lung cancer patients, the underlying mechanisms were poorly understood." (PMID 29484139, 2018). "EGFR-TKIs are used to treat lung cancers with EGFR mutations, and studies have shown that EGFR-TKI treatment of patients with brain metastasis is also related to EGFR mutations." (PMID 29435193, 2018). "Mutation and/or amplification of the EGFR gene leading to aberrant activation of downstream signaling pathways are critical mechanisms promoting tumorigenesis, especially in lung cancer." (PMID 29548337, 2018).
lung cancer (continued). "EGFR represent RTKs family as the well-studied kinase, implicated in several human cancers including lung cancer, glioblastoma, breast cancer, cervical carcinoma and related mutations." (PMID 29455673, 2018). "In the case of lung cancer, it is well known that EGFR-activating mutations can be used as a biomarker to stratify patients for EGFR TKI treatment as lung cancer harboring EGFR mutations is addicted to EGFR activation and thus sensitive to EGFR TKIs." (PMID 30449278, 2018). "All lung cancers patients with epidermal growth factor receptor (EGFR) mutation inevitably develop acquired resistance to EGFR tyrosine kinase inhibitors (TKI)." (PMID 29717264, 2018). "A study in lung cancer found a genetic context to the dual effects of ZEB1 with ZEB1 serving as an oncogene in KRAS-mutated lung cancer but as a tumor suppressor in EGFR-mutated lung cancer cells." (PMID 32309604, 2018). "We recently showed in a large series of lung cancer patients that besides allowing the identification of EGFR, KRAS, and BRAF mutations, NGS identified a potential driver in 36% of patients (FGFR, ERBB2, AKT, MAP2K1, STK11...)." (PMID 29890761, 2018). "In lung cancer, mutations of epidermal growth factor receptor (EGFR) are a predictive marker of response to tyrosine kinase inhibitors (TKIs)." (PMID 29515761, 2018). "With the European Medicines Agency (EMA) approval of a third generation TKI for advanced NSCLC patients, the request for EGFR T790M resistance mutation detection for stratification of lung cancer patients eligible for treatment increased significantly." (PMID 29719623, 2018). "Another study demonstrated PIK3CA mutations in 5% of lung cancer patients having EGFR mutations with acquired resistance." (PMID 29973561, 2018). "Recently development of personalized treatment to lung carcinoma has attracted more attention to EGFR mutations." (PMID 30547844, 2018). "We surveyed the prognostic value of EGFR mutations in a cohort of 573 patients from East China who underwent surgical resection of pathological T1 lung carcinoma." (PMID 29849818, 2018). "Epidermal growth factor receptor‐tyrosine kinase inhibitor (EGFR‐TKI) is effective in lung cancer patients carrying sensitive EGFR mutations." (PMID 28097086, 2017). "It is needed that the lung cancer cell lines with EGFR mutations which are sensitive to gefitinib are tested in this study." (PMID 28854941, 2017). "Somatic mutation in epidermal growth factor receptor (EGFR) is one of the driver mutations in lung cancer." (PMID 28152008, 2017). "We have found that KEAP1 loss modulates sensitivity to inhibition of EGFR, ALK, BRAF, or MEK in lung cancer cell lines with EGFR, ALK, BRAF, KRAS, or NRAS mutations." (PMID 28145866, 2017). "Engineered Ba/F3 cells overexpressing triple-mutant EGFR were shown to be sensitive to brigatinib not only in vitro but also in vivo, as were the lung cancer cell lines with the triple-mutation in vitro." (PMID 28287083, 2017). "Mutations in genes related to the Wnt pathway were also implicated in erlotinib resistance in EGFR mutation positive lung cancer cell lines." (PMID 28854272, 2017). "Given the genotoxicity of 4-OHEs and the high frequency of acquired EGFR mutations in Asian women with lung cancer, it will be important to determine if 4-OHEs accelerate the rate of EGFR mutation." (PMID 29290988, 2017). "Although early-stage lung cancer patients with EGFR mutations exhibit a higher correlation with lower USP24 expression, other patients (especially at the late stage) express higher levels of USP24." (PMID 27991932, 2017). "At present, molecular-targeted therapies of lung cancer are confined to those targeting EGFR and ALK mutations." (PMID 28415711, 2017). "MCT-1 expression was largely positively associated with YY1 (Phi coefficient +0.27, P=0.003), EGFR (Phi coefficient +0.43, P<0.001) and MnSOD (Phi coefficient +0.59, P<0.001) in all stages of lung cancers." (PMID 28394354, 2017).
lung cancer (continued). "In lung cancer, EGFR is also overexpressed, and in a subset of lung cancers EGFR is mutated, rendering the receptor constitutively activated." (PMID 28338617, 2017). "The Chinese CTONG trial compared adjuvant TKI therapy with gefitinib for two years to the standard of care with 4 cycles of cisplatin/vinorelbine in patients with EGFR-mutated lung cancer." (PMID 29250201, 2017). "Why patients with family history of lung cancer have a higher prevalence of EGFR activating mutation has been poorly understood." (PMID 28486527, 2017). "In the 2004 studies, most of the lung cancer patients responding to EGFR TK inhibitors (TKIs), such as erlotinib and gefitinib, reportedly had EGFR mutations." (PMID 28832323, 2017). "In a study evaluating the diagnostic accuracy of detecting EGFR in lung cancer by deep sequencing of plasma cfDNA, the overall sensitivity was 54.4% for all cases." (PMID 27926526, 2017). "Clinical observations showed that lung cancer patients with EGFR mutations who developed TKI-resistance and received chemotherapy as the second-line treatment remained responsive to the original TKIs as the third-line treatment." (PMID 28683123, 2017). "HER2 blockade (trastuzumab) in HER2-positive breast cancer, tyrosine kinase inhibitor in CRC and chronic myelogenous leukemia, and inhibitors of EGFR in EGFR-mutated lung cancer are clinically established as examples of targeted therapy." (PMID 28813639, 2017). "With regard to molecular features, several studies found that both EGFR mutations and ALK rearrangements were less prevalent in COPD-associated lung cancer, and the presence of EGFR mutations was inversely correlated with the severity of airflow limitation." (PMID 28061470, 2017). "Approval of osimertinib will influence the treatment tactics for EGFR-mutated lung cancer, but, again, resistance to osimertinib will be a major obstacle." (PMID 28287083, 2017). "In this retrospective, nationwide, longitudinal cohort study, statin use was associated with prolonged PFS and OS in patients with lung cancer receiving EGFR-TKI therapy." (PMID 28158206, 2017). "In our previous study, we also found that EMT, another non-T790M mediated resistance mechanism to EGFR-TKIs, decreased PD-L1 expression in lung cancer cells with an EGFR mutation." (PMID 29119113, 2017). "For example, the College of American Pathologists, the International Association for the Study of Lung Cancer and the Association for Molecular Pathology have recommended the use of cytological materials in EGFR mutation testing since October 2013." (PMID 28938658, 2017). "Combined, these results show that doublet therapies had a significant effect on lung cancer cells harboring EGFR T790M mutations; however, there is room for improvement in terms of the magnitude of remission and toxicity." (PMID 28388009, 2017). "In summary, studies have been focused on the underpinning mechanisms the resistance for anti-EGFR agents, and EGFR mutations play a pivotal role in lung cancer." (PMID 28430586, 2017). "Taken together, these results demonstrate that loss of ING5 enhances aggressiveness of lung cancer cells by promoting EMT via activation of EGFR/PI3K/Akt and IL-6/STAT3 signaling pathways." (PMID 28903339, 2017). "An example is the common EGFR T790M “gatekeeper” mutation, which occurs after first generation anti-EGFR therapy in lung cancer and hinders drug binding." (PMID 28431544, 2017). "Liu and co-workers argued that a case with three lung cancers, all with the same EGFR mutation, still were likely to be synchronous tumours based on about 40 discordant non-driver mutations found with WES." (PMID 28347348, 2017). "The study included consecutive 829 non-small-cell lung cancer patients who received analysis of EGFR mutation in a prospective lung cancer cohort." (PMID 28486527, 2017).
lung cancer (continued). "The need for improved therapies for these patients is accentuated by recent data demonstrating significantly shorter DFS of EGFR mutated stage 3 lung cancer patients compared to wild type patients." (PMID 29029422, 2017). "In this regard, family histories of lung cancer have been thought to add information in predicting risk for lung cancer and prevalence of mutations on epidermal growth factor receptor (EGFR) gene." (PMID 28486527, 2017). "Currently, there are two assays approved by the FDA for testing EGFR mutations in lung cancers, the cobas EGFR mutation test (Roche Molecular Systems, Branchburg, NJ) and the therascreen EGFR RGQ PCR Kit (Qiagen, Hilden, Germany)." (PMID 29228562, 2017). "At present, most of the approaches in routine practice use plasma, in particular for activating and resistance mutations detection in EGFR in patients with advanced stage lung cancer." (PMID 28805673, 2017). "This will likely propel development of further NGS-based EGFR mutation detection assays, which are of particular relevance for the Asian population in which EGFR mutation-positive lung cancers occur more frequently than in the Caucasian population." (PMID 28381299, 2017). "In this way, this agreement study has provided evidence of the clinical validity of the RT-PCR and MS tests for detecting EGFR gene mutations in lung cancer patients." (PMID 29254176, 2017). "For instance, several mutations found in lung cancer are located in the tyrosine kinase (TK) domain of EGFR." (PMID 27956147, 2017). "Loss of E-cadherin, an epithelial marker, sensitizes lung cancer cells with primary EGFR mutations to TKI treatments and is correlated with the poor prognosis of lung cancer patients." (PMID 28683123, 2017). "In recent years, epidermal growth factor receptor tyrosine kinase inhibitors (EGFR‐TKIs) are clinically effective in patients with non–small cell lung cancer (NSCLC) harboring sensitizing EGFR mutations." (PMID 28000387, 2017). "To further confirm that RHOB expression impacts on the response to EGFR‐TKI treatment, we downregulated or overexpressed RHOB by RNA interference and adenoviral transduction, respectively, in several EGFR‐mutated human lung cancer cell lines." (PMID 28003335, 2017). "In our cohort, we identified eight lung cancer patients with EGFR C797S mutation occurring in cis with EGFR T790M mutation; in one patient, serial sampling confirmed that the EGFR C797S mutation occurred after the AZD9291 therapy." (PMID 29123093, 2017). "The retesting study described here demonstrates moderately high agreement between a RT-PCR and a MS test for detecting EGFR gene mutations in lung cancer patients." (PMID 29254176, 2017). "In the 47 biopsies diagnosed with lung cancer, EGFR mutation tests were examined in 23 cases and the total mutation rate of bone metastasis was 30.4 % (7/23)." (PMID 27444682, 2017). "Sanger sequencing of some lung cancer families found an association between lung cancer and the T790M mutation in EGFR." (PMID 28106732, 2017). "Differences in SUVmax and serum levels of tumor markers among different histological types of lung cancers and between EGFR mutation statues of adenocarcinoma were compared." (PMID 28877268, 2017). "Here, we assessed the National Lung Cancer database from the Taiwan Cancer Registry from 2011 to 2014 to investigate the impact of the smoking status on the EGFR mutation rate and the survival time of advanced lung adenocarcinoma patients." (PMID 29228697, 2017). "The 4 retrospective studies that previously investigated the correlation between the 18F-FDG uptake and EGFR mutation status in lung cancer reported contradictory findings." (PMID 28422979, 2017). "Randomized phase III studies have consistently demonstrated that first-line EGFR-TKI therapy improves progression-free survival (PFS) compared with standard cytotoxic chemotherapy in EGFR mutated lung cancer patients." (PMID 29029416, 2017).